IL2 (interleukin 2)
Diseases named in the same sentence as IL2 in open-access papers (continued):
Sharing a sentence is not in itself a finding about the gene and the disease.
membranous nephropathy (1 paper, 2018). "Significantly higher frequency of CD4+/CXCR5+, CD4+/CXCR5+/ICOS+ and CD4+/CXCR5+/PD-1+ TFH cells, and higher serum levels of IL-17A, IFN-γ, IL-2, IL-10, IL-4 and IL-21 were detected in hepatitis B virus-associated membranous nephropathy patients compared to the healthy controls." (PMID 28770269, 2018).
metabolic acidosis (1 paper, 2014). "Metabolic acidosis defined by decreased serum bicarbonate levels is another severe IL-2-related toxicity that can arise from lactic acid production by proliferating T cells." (PMID 24855563, 2014).
metastatic squamous cell carcinoma (1 paper, 2021). A squamous cell carcinoma which has spread from its original site of growth to another anatomic site. "A phase II clinical trial evaluating adoptive cell therapy with autologous tumor infiltrating lymphocytes infusion followed by IL-2 for the treatment of patients with recurrent and/or metastatic squamous cell carcinoma of the head and neck is currently active (NCT03083873)." (PMID 34277428, 2021).
microcephaly (1 paper, 2021). A congenital or acquired developmental disorder in which the circumference of the head is smaller than normal for the person's age and sex. "Conversely, ZIKV-exposed participants without microcephaly displayed a general trend to decrease concentrations of inflammation mediators as IL-2, IL-4, IL-12p40, IL-12p70, TNF-α, TNF-β, IFN-γ, and the growth factors GCSF and EGF." (PMID 33875756, 2021).
morbid obesity (1 paper, 2022). An excess of body weight, normally defined as an individual with a body mass index greater than 35 or a body weight greater than one hundred percent of ideal body weight. "The IL-2 and IFN-γ producing capacity of CD8+ T cells was significantly decreased by morbid obesity, which was not influenced by bariatric surgery." (PMID 35860273, 2022).
mucosa-associated lymphoid tissue lymphomas (1 paper, 2024). "This response may be accompanied by IL-8, IL-2, CXCL-9 and CXCL-10 to the site of inflammation, with excess immune overstimulation by persistent antigens creating B-lymphocyte hyperplasia, triggered by T-cells, which can lead to mucosa-associated lymphoid tissue lymphomas." (PMID 39608222, 2024).
mucosal melanoma (1 paper, 2024). A melanoma that arises from a mucosal site. "However, dacarbazine has shown benefits in 10%-20% of patients with mucosal melanoma, whether administered alone or in combination with high-dose interferon and IL-2." (PMID 39449907, 2024).
mycobacterial infections (1 paper, 2012). "In fact, HMBPP plus IL-2 treatment or mycobacterial infections can rapidly induce up to 400-fold expansion of Vγ2Vδ2 T cells or up to 80% from a baseline level 1% of CD3+ T cells." (PMID 22319574, 2012).
myopia (1 paper, 2024). "In this two-sample MR study, we explored the causal relationship between exposure to 27 inflammatory cytokines and the development of myopia, identifying a potential pathogenic association with IL-2 and IL-2ra." (PMID 39239046, 2024). "Elevated levels of inflammatory factors, especially IL-2 and IL-2ra, have a potential causal relationship with myopia susceptibility, providing new insights into the pathogenesis of myopia." (PMID 39239046, 2024). "Our findings suggest that elevated levels of IL-2 and IL-2ra may increase the risk of developing myopia, offering new insights into the pathogenesis of myopia." (PMID 39239046, 2024). "This study investigates their relationship using genetic variation as an instrumental variable, revealing a positive correlation with myopia development and marking the first observation of increased IL-2 expression in the vitreous of FDM guinea pigs." (PMID 39239046, 2024). "The expression of interleukin-2 (IL-2) in the vitreous of guinea pigs subjected to experimentally induced form-deprivation myopia (FDM) was examined." (PMID 39239046, 2024). "Experimental validation: Through the examination of IL-2 expression in guinea pigs subjected to form-deprivation myopia (FDM), the study not only corroborates its genetic findings but also enriches the understanding of myopia’s pathogenesis from an experimental perspective." (PMID 39239046, 2024). "Elevated concentrations of IL-2 and IL-2ra were found to be associated [IVW estimate odds ratio (OR): 1.003, 95% CI: 1.001–1.005, P=0.001] and strongly associated (IVW estimate OR: 1.002, 95% CI: 1.000–1.003, P=0.049) with an increased risk of myopia, respectively." (PMID 39239046, 2024). "However, the correlation between IL-2, IL-2Rα, and myopia has been less explored." (PMID 39239046, 2024). "Noteworthy findings include significant associations of IL-2 [IVW odds ratio (OR): 1.003, 95% CI: 1.001–1.005, P=0.001], IL-2ra (IVW OR: 1.002, 95% CI: 1.000–1.003, P=0.049), CRP (IVW OR: 0.996, 95% CI: 0.994–0.999, P=0.002), and TNF-α (IVW OR: 0.995, 95% CI: 0.994–0.996, P<0.001) with myopia risk." (PMID 39239046, 2024).
neonatal encephalopathy (1 paper, 2025). "Additionally, elevated levels of TNF-β and IL-2 have been reported at school age in children with a history of neonatal encephalopathy." (PMID 40948499, 2025).
Neurodevelopmental delay (1 paper, 2020). "By contrast, in the absence of alcohol-exposure, activation of a network including IL-2, TNF-β, IL-10, and IL-15 was associated with neurodevelopmental delay." (PMID 31992316, 2020). "Control children experiencing neurodevelopmental delay (C/ND) showed activation of what we defined as the Alcohol-Independent Delay Network (network 1) that included IL-2, TNF-β, IL-10, and IL-15." (PMID 31992316, 2020). "Children with alcohol-independent neurodevelopmental delay (C/ND) showed activation of a single network, the Alcohol-Independent Neurodevelopmental Delay Network (network 1; IL-2, IL-15, TNF-β, and IL-10)." (PMID 31992316, 2020). "Network 1 included IL-2, TNF-β, IL-10, and IL-15 and was defined as the Alcohol-Independent Delay Network, as this network was activated specifically in controls with neurodevelopmental delay." (PMID 31992316, 2020). "For controls, we found higher average levels of a subset of cytokines including IL-4, IL-1β, PlGF, GM-CSF, SAA, IL-15, TNF-β, VEGF-D, IL-12p70, Tie-2, IL-2, IL-17α, IFN-ɣ, and IL-10 in children with neurodevelopmental delay (C/ND), compared to that of their typically developing (C/TD) counterparts." (PMID 31992316, 2020). "Based on our findings, we propose that elevations in IL-2, IL-15, TNF-β, and IL-10 may represent a non-specific immune profile broadly associated with neurodevelopmental delay during childhood, rather than serving as a more specific biomarker of any one neurodevelopmental disorder." (PMID 31992316, 2020).
NK/T cell lymphoma (1 paper, 2015). "Thus it is important to understand the mechanism of IL-2(−)-induced apoptosis to develop novel treatments for drug-resistant NK/T cell lymphoma." (PMID 25855965, 2015).
oligoarticular JIA (1 paper, 2023). "Upregulation of the IL-2-pathway suggests a role for anti-T cell strategies such as JAK-STAT inhibitors or cyclosporine in some refractory polyarticular/oligoarticular JIA patients." (PMID 36793127, 2023).
Onset (1 paper, 2019). The age group in which disease manifestations appear. "It has also been shown that increased levels of cytokines such as IL-2, IL-6, IL-8, TNF-α in subjects with new-onset AF, can stimulate mesothelial cells to produce CA125." (PMID 31058877, 2019).
optic neuritis (1 paper, 2023). Optic neuritis is inflammation of the optic nerve, the nerve that carries the visual signal from the eye to the brain.The conditionmay cause sudden, reduced vision in the affected eye(s). "Collectively, these data suggest that elevation of IL-2 levels in the context of viral infection drives an auto-aggressive IL-17A response that causes optic neuritis and CNS pathology." (PMID 36817487, 2023). "To provide a framework for analysis of potential multifactorial interactions, we developed a mouse model of optic neuritis that combines overexpression of interleukin-2 (IL-2) in the context of HSV-1 infection using the recombinant HSV-IL-2 virus." (PMID 36817487, 2023).
oral lichen planus (1 paper, 2020). Oral lichen planus is a chronic inflammatory oral condition of unknown aetiology characterized by T-cell-mediated chronic immune response and abnormal epithelial keratinization cycle. "Other studies comparing salivary cytokines of clinical samples and controls found increased expression of IL-2 and IL-4 in smokers and in patients with oral lichen planus (a chronic inflammatory disease that affects the oral mucosa)." (PMID 31973090, 2020).
oral mucositis (1 paper, 2015). Inflammation of the mucous membranes of any of the structures in the mouth. "An increase in salivary IL-2 level most probably results from a micro-injury of oral mucosa following administration of cytostatics, which destroy quickly dividing cells, which in turn may cause oral mucositis in children with ALL." (PMID 25976216, 2015).
oral squamous cell carcinoma (1 paper, 2020). "Therefore, salivary biomarkers like the pro-inflammatory cytokines IL-1β, IL-2 and TNF might be used as a future diagnostic tool for oral squamous cell carcinoma." (PMID 33153049, 2020).
Osteochondroma (1 paper, 2022). A common, benign cartiliginous neoplasm arising from the metaphysis of bone. "There were two SAEs reported in the Ld-IL2 group, including surgery for osteochondroma not related to the study and worsening of RA." (PMID 35250032, 2022).
osteomyelitis (1 paper, 2023). An acute or chronic inflammation of the bone and its structures due to infection with pyogenic bacteria. "Their finding inspires us that IL-2 or muPD1-IL2v may exert a similar effect to enhance the immune response in chronic osteomyelitis." (PMID 37744377, 2023). "They demonstrated that luteolin, chryseriol, kaempferol, and quercetin are the main active compounds of WWXDD, which are capable for downregulating the percentage of Treg cells via IL-2/STAT5 and suppressing the increased level of Foxp3 and CTLA-4 in osteomyelitis." (PMID 37744377, 2023).
ovarian endometriosis (1 paper, 2023). A non-neoplastic disorder characterized by the growth of endometrial tissue in the ovaries. "IL-2 RB can induces growth potential for endometrial glandular epithelial cells, and its hypermethylation and downregulation has been found in ovarian endometriosis." (PMID 36911409, 2023).
overactive bladder (1 paper, 2026). Symptom of overactive detrusor muscle of the urinary bladder that contracts with abnormally high frequency and urgency. "Patients with an overactive bladder (OAB) have been found to have increased mRNA levels of some urine biomarkers associated with inflammation (such as TNFα, IL2, NGF)." (PMID 41596750, 2026).
panniculitis (1 paper, 1992). Inflammation of the subcutaneous adipose tissue. "We report here a patient who developed a lobular panniculitis at the site of sc IL-2 injection which prevents continuation of sc therapy." (PMID 1419609, 1992).
parvovirus infection (1 paper, 2021). "Although the cell-mediated immune response to placental parvovirus infection is not well characterized, one study noted a significant increase in interleukin-2 (IL-2) production in placentas from women with parvovirus B19 infections compared to uninfected placentas." (PMID 33805739, 2021).
penile squamous cell carcinoma (1 paper, 2025). "Immunohistochemistry (IHC) analysis of eight cytokines (IL-1A, IL-1B, IL-2, IL-6, IL-12, TGF-β1, TNF-α and IFN-γ) was performed in paired tumour tissues and corresponding negative surgical margins from 94 patients with penile squamous cell carcinoma." (PMID 41465261, 2025).
peripheral neuroectodermal tumor (1 paper, 2020). "Furthermore, IL2-secreting fibroblasts were shown to increase the NKT-cell counts in patients with peripheral neuroectodermal tumor and, subsequently tumor cell death." (PMID 32560387, 2020).
periventricular leukomalacia (1 paper, 2023). Periventricular leukomalacia (PVL) is a brain injury disorder characterized by the death of the white matter of the brain due to softening of the brain tissue. "IL‐2, reported to be toxic to oligodendrocytes and myelin, could play a role in the molecular cascade leading to white matter damage in periventricular leukomalacia." (PMID 38054663, 2023).
pharyngitis (1 paper, 2025). Inflammation of the throat most often caused by viral and bacterial infections. "MAIT cells are highly activated to release IFNγ, IL-1β, IL-2 and TNF, which are involved in pharyngitis, invasive GAS disease and ARF." (PMID 40276383, 2025).
pneumococcal meningitis (1 paper, 2012). An acute purulent infection of the meninges and subarachnoid space caused by Streptococcus pneumoniae, most prevalent in children and adults over the age of 60. "IL-1β, IL-2, IL-4, IL-10, IL-12p70, IL-17, RANTES, TNF-α, IL-18 and IL-33 were not significantly altered in the plasma of mice with pneumococcal meningitis compared to sham controls." (PMID 22455545, 2012). "IL-2, IL-4, IL-10, IL-12p70, IL-17, IFN-γ, TNF-α, IL-18 and IL-33 were not altered in brain homogenates of mice with pneumococcal meningitis compared to sham controls." (PMID 22455545, 2012).
pneumonic plague (1 paper, 2024). A plague in which the bacteria have infected the lungs. "The study started with a comparison of the immunogenicity and efficacy of the rF1V vaccine formulated with IL-2 and/or GM-CSF adsorbed to Alhydrogel in a mouse model of pneumonic plague." (PMID 38605961, 2024).
polycystic ovarian syndrome (1 paper, 2022). "Rimonabant treatment for 12 weeks in obese women with polycystic ovarian syndrome resulted in increased circulating levels of VEGF however, the treatment did not alter TNF-α, IL-1β, IL-2, and IL-6, which is in contrast to our results following AM251 treatment." (PMID 36232744, 2022).
polyneuropathies (1 paper, 2023). "While confirming previous data of an elevated systemic IL-2 gene expression in SFN patients, higher systemic IL-2 RNA levels were also found in PBMC of patients with painful polyneuropathies of various etiologies compared to controls." (PMID 36604634, 2023).
porocarcinoma (1 paper, 2020). "We propose that the use of intralesional IL-2 in the treatment of metastatic porocarcinoma warrants further investigation and represents a potential disease altering treatment for a rare and aggressive malignancy." (PMID 33704189, 2020). "Given that all other treatment modalities had been attempted and failed, the multidisciplinary team decided to proceed with the novel use of intralesional IL-2 in the treatment of this patient’s porocarcinoma." (PMID 33704189, 2020). "The use of intralesional IL-2 for porocarcinoma has, to our knowledge, only been described once before in the literature." (PMID 33704189, 2020). "At this point, the patient has completed his intralesional IL-2 treatment, and has no clinical, pathologic, or radiographic evidence of porocarcinoma ten months after his last treatment of IL-2." (PMID 33704189, 2020). "Since completing treatment with IL-2, he has undergone a surveillance PET CT scan 6 months after the last dose of IL-2, which revealed no definitive active disease, and biopsies of two separate persistent lesions demonstrated fibrosis without evidence of porocarcinoma." (PMID 33704189, 2020).
posterior uveitis (1 paper, 2012). Inflammation of the choroid as well as the retina and vitreous body. "Taking together, we hypothesize that CFH-rs800292, IL-27-rs4788084, and rs4505848 within the KIAA1109/Testis nuclear RNA-binding protein (Tenr)/IL2/IL21 gene cluster might be involved in the pathogenesis of IU and posterior uveitis." (PMID 22876110, 2012).
posttraumatic stress disorder (1 paper, 2021). "Elevated IL-2, 24 h after injury, is associated more severe early post-concussive symptoms, while elevated plasma IL-10 level at 6 months is associated with more severe posttraumatic stress disorder (PTSD) and mood scores." (PMID 33679762, 2021).
prion disease (1 paper, 2021). A transmissible disease that is caused by a protein that is able to induce abnormal folding of normal cellular proteins, leading to characteristic spongiform brain changes, which are associated with neuronal loss without an inflammatory response. "Taken together, although DEX treatment has had no apparent effect in modulating the levels of this peptide, a role of IL-2 in prion diseases should not be discarded before developing further studies." (PMID 33540568, 2021).
proliferative vitreoretinopathy (1 paper, 2019). Vitreoretinal membrane shrinkage or contraction secondary to the proliferation of primarily retinal pigment epithelial cells and glial cells, particularly fibrous astrocytes, followed by membrane formation. "The expression level of IL‐2 has been found to be highly expressed in the aqueous humour of polypoidal choroidal vasculopathy (PCV) and proliferative vitreoretinopathy (PVR) patients." (PMID 31608440, 2019). "IL‐2 promotes cell migration, ECM synthesis and TGF‐β2 expression in RPE cells via JAK/STAT3 and NF‐κB signaling pathways, which may play an important role in proliferative vitreoretinopathy." (PMID 31608440, 2019).
psychological distress (1 paper, 2022). "In conclusion, we found that psychological distress was associated with the cytokines IL-2, IL-4, IL-5, IL-10, IL-12, TNF-α, and IFN-γ." (PMID 36405903, 2022). "However, psychological distress was significantly associated with the plasma cytokines IL-2, IL-4, IL-5, IL-10, IL-12, TNF-α and IFN-γ." (PMID 36405903, 2022).
pulmonary fungal infection (1 paper, 2015). "Hence, IL-2 complexes can be used to augment the Th2 cell response during pulmonary fungal infection and assess the relationship between Th2 cells and fungal disease." (PMID 25764512, 2015).
pulmonary sarcoma (1 paper, 2021). "The first studies in murine tumor models revealed that administration of LAK cells alone did not lead to reduced growth of pulmonary metastases, while simultaneous administration of LAK cells and IL-2 resulted in a significant reduction in established pulmonary sarcoma metastases." (PMID 33807011, 2021).
pyometra (1 paper, 2025). "(2014), TNF‐α, IFN‐γ, IL‐2, IL‐4 and IL‐10 cytokine concentrations were found to be high in dogs with pyometra." (PMID 39792082, 2025).
Pythiosis (1 paper, 2022). A granulomatous disease caused by the aquatic organism PYTHIUM insidiosum and occurring primarily in horses, cattle, dogs, cats, fishes, and rarely in humans. "The mechanism behind P. insidiosum antigen (PIA) immunotherapy in human pythiosis includes a switching from the host’s T helper-2 (Th2) to T helper-1 (Th1) mediated immune response in the host; the Th1 response producing higher levels of interferon-γ (IFN-γ) and interleukin 2 (IL-2)." (PMID 35453202, 2022).
red cell aplasia (1 paper, 2016). "It was concluded that IL-2 was the cause of her red cell aplasia." (PMID 27144182, 2016).
reticulum cell sarcoma (1 paper, 1999). An antiquated term that refers to a non-Hodgkin lymphoma composed of diffuse infiltrates of large, often anaplastic lymphocytes. "The possibility of using interleukin 2 (IL-2)-activated natural killer cells (A-NK) to carry methoxymorpholinyl doxorubicin (MMDX; PNU 152243) to liver-infiltrating tumours was explored in mice bearing 2-day established M5076 reticulum cell sarcoma hepatic metastases." (PMID 10098738, 1999).
rhabdomyolysis (1 paper, 2018). Necrosis or disintegration of skeletal muscle often followed by myoglobinuria. "As the literature shows, rhabdomyolysis has not been reported as a toxicity related to HD IL-2 therapy alone." (PMID 29898784, 2018).